EZH2 (enhancer of zeste 2 polycomb repressive complex 2 subunit)
Diseases named in the same sentence as EZH2 in open-access papers (continued):
Sharing a sentence is not in itself a finding about the gene and the disease.
glioma (continued). "While preclinical studies are ongoing, caution is necessary when considering using EZH2 inhibitors in other glioma models, as EZH2 may have context-specific functions and various downstream effects such as regulation of tumor suppressors or other signaling pathways." (PMID 38183103, 2024). "Therefore, targeting SPRY4‐IT1/miR‐101‐3p/EZH2/VEGFA axis may improve the outcomes of patients with glioma." (PMID 36479622, 2023). "SNHG7 may enhance the proliferation of glioma by regulating the miR-138-5p/EZH2 signal axis." (PMID 35127343, 2022). "In pediatric high-grade gliomas, specifically diffuse midline gliomas (DMG) which is characterized by the signature K27M mutation in histone H3, EZH2 ablation promotes tumor cell proliferation, while EZH2 overexpression reverses this effect in H3WT DMG mouse models." (PMID 36263120, 2022). "Additionally, as there are no known mutations of the PRC2 genes in high grade gliomas, the mechanism of the effect of EZH2 remains context dependent." (PMID 35395831, 2022). "The expression of LINC00963 induced by EZH2 signaling could prevent apoptosis in glioma cells." (PMID 36389690, 2022). "Therefore, these existing results suggested that exosomal miR-133b could attenuate glioma development by disrupting the Wnt/β-catenin signaling pathway and inhibiting EZH2." (PMID 36438184, 2022). "Likewise, in gliomas, EZH2 aberrant expression is a predictor of poor prognosis." (PMID 36292072, 2022). "Our study revealed that in IDH1 R132H-negative gliomas, EZH2 overexpression predicted significantly poorer PFS and OS outcomes with a higher recurrence risk (p = 0.001) and 4.7 times higher mortality (p = 0.025) than IDH1 R132H-negative gliomas with low EZH2 expression." (PMID 36292072, 2022). "Another angiomiR involved in glioma blood vessel development is MiR-137, which inhibits proliferation and angiogenesis of human glioblastoma cells by targeting enhancer of zeste homolog 2 (EZH2), an enzyme participating in histone methylation and transcriptional repression." (PMID 34200145, 2021). "Thus, EZH2 may be a possible biomarker and therapeutic target in gliomas as well as in the development of novel treatment schemes that target both the genetic and epigenetic mechanisms of gliomagenesis." (PMID 34745848, 2021). "Moreover, in vivo studies verified MSC-derived exosomes’ ability loaded with miR-133b to inhibit glioma tumor growth, and MSC-derived exosomal miR-133b and the Wnt/β-catenin/EZH2 pathway could act as biomarkers for monitoring and prognosis in glioma therapy." (PMID 34722277, 2021). "Furthermore, we show that DLGAP1-AS1 could regulate EZH2 expression and promote glioma cell invasion, migration and proliferation through miR-1297 sponging." (PMID 33901010, 2021). "Thus, EZH2 is a promising therapeutic as well as prognostic biomarker for the treatment of glioma." (PMID 34745848, 2021). "Furthermore, they indicated that EZH2 immunohistochemistry was capable of differentiating nonneoplastic reactive glial proliferation from gliomas, thus showing its diagnostic application in routine neuropathology practice." (PMID 34745848, 2021). "Thus, the blockade of EZH2 expression in glioma could be of therapeutic value for patients with glioma." (PMID 34745848, 2021). "In addition, a prior study showed that EZH2 inhibition could be involved in the therapy targeting cancer stem cells for glioma." (PMID 33363140, 2020). "Hence, EZH2/miR-454-3p/PTEN axis modulated macrophage M2 polarization in glioma." (PMID 33363140, 2020). "Therefore, our study aimed to identify whether EZH2 regulated M2 macrophage polarization in glioma via miR-454-3p." (PMID 33363140, 2020). "Finally, MSC-derived exosomal miR-133b and the Wnt/β-catenin/EZH2 pathway could act as biomarkers for monitoring and prognosis in glioma therapy." (PMID 32746854, 2020).
glioma (continued). "In addition, another study reported that depletion of EZH2 could repress the proliferation of glioma cells, while we witnessed a similar function in the current study." (PMID 31842978, 2019). "Furthermore, bioinformatics analysis predicted that miR-133b could target the Enhancer of Zeste 2 (EZH2) gene in glioma." (PMID 31842978, 2019). "In conclusion, our finding evidenced that MSC-derived exosomes transferring miR-133b into glioma cells could potentially inhibit EZH2 expression via blocking the Wnt/β-catenin signaling pathway, thereby suppressing cell proliferation, migration, and invasion in glioma." (PMID 31842978, 2019). "Indeed, we observed significant positive correlations between 13-gene scores and EZH2 levels in glioma (rho = 0.45; P < 0.0001), clear cell renal cell (rho = 0.22; P < 0.0001), papillary renal cell (rho = 0.33; P < 0.0001) and liver (rho = 0.26; P < 0.0001) cancers." (PMID 31523055, 2019). "In addition, the TCGA database also demonstrated that EZH2 was highly expressed in glioma samples." (PMID 31842978, 2019). "Thus, MSCs affected miR-133b and EZH2 expression in glioma cells." (PMID 31842978, 2019). "Furthermore, glioma cells were co-cultured with MSC-derived exosomes treated with miR-133b mimic or inhibitor, and EZH2-over-expressing vectors or shRNA against EZH2 to characterize their effect on proliferation, invasion, and migration of glioma cells in vitro." (PMID 31842978, 2019). "Additionally, the in vitro and in vivo experiments performed in our study revealed that MSC-derived exosomal miR-133b inhibited glioma cell proliferation, invasion, and migration and tumor growth by reducing EZH2 by inhibiting the Wnt/β-catenin signaling pathway." (PMID 31842978, 2019). "Moreover, EZH2 silencing resulted in inhibited glioma cell proliferation, invasion, and migration." (PMID 31842978, 2019). "Therefore, LINC00526/EZH2/AXL/PI3K/Akt/NF‐κB form a feedback loop in glioma." (PMID 31240814, 2019). "Moreover, we demonstrated that HOXB13‐AS1 could contribute to glioma cell proliferation by binding with the enhancer of zeste homolog 2 (EZH2), epigenetically suppressing its neighbor gene HOXB13 expression." (PMID 30105866, 2018). "Therefore, focusing on EZH2 as a new target may pave a new way for the treatment of clinical glioma." (PMID 30498431, 2018). "In addition, as the gene enhancer of zeste homolog 2 (EZH2) serves as an oncogene and is required for cancer stem cell maintenance, the inhibition of EZH2 by lncRNAs can effectively promote the therapeutic sensitivity in gliomas." (PMID 28293170, 2017). "Importantly, we first found that PVT1 may regulate glioma proliferation and invasion via target EZH2." (PMID 29046366, 2017). "It is known that increased EZH2 expression correlates with glioma grade and its recurrence, suggesting that EZH2 could be a marker of glioma aggressiveness and correlate with a decreased GBM patient survival, and the EZH2 protein was found to be strongly expressed in U87 cell lines." (PMID 28642877, 2017). "In addition, EZH2 was more expressed in GBM than in low-grade glioma, and inhibition of EZH2 expression by shRNA could decrease glioma cell proliferation, and high expression of EZH2 was determined to be an independent predictor of short overall survival." (PMID 29046366, 2017). "Our results provide the evidence that EZH2 might be applied as a potential biomarker for glioma." (PMID 27880940, 2017). "Importantly, restoring EZH2 expression could override miR-524-5p and miR-324-5p function in glioma cells." (PMID 29221202, 2017). "Thus, EZH2 has been investigated as a potential chemotherapeutic target for gliomas." (PMID 24867641, 2014). "A recent study shows that the number of tumor cells with nuclear localization of EZH2 is larger around tumor vessels and the invasive front in human glioma specimens, suggesting that nuclear EZH2 could contribute to glioblastoma-induced angiogenesis and invasion." (PMID 24202337, 2013).
glioma (continued). "Finally, AXL expression is found in human gliomas with high EZH2 expression." (PMID 23077658, 2012). "Stress-induced chromatin remodeling (e.g., via EZH2, H3K27ac modifications) and downstream transcriptional shifts (e.g., STAT3 activation) promote return to a resilient glioma stem cell phenotype." (PMID 41614813, 2025). "IHMT-337 targets EZH2 in vitro to inhibit WNK1 activation, thereby suppressing glioma cell migration." (PMID 38886655, 2024). "EZH2 can activate the WNK1-OSR1-NKCC1 cascade by regulating KCC2 expression, thereby regulating glioma migration." (PMID 38886655, 2024). "Compared to parental cells, TMZ-resistant glioma cells expressed higher levels of ATRX and were enriched in EZH2." (PMID 39479502, 2024). "In conclusion, this study reaffirms the relationship between EZH2 and glioma progression, revealing EZH2's role in regulating SLC12A5 expression by methylating its promoter region, thereby impacting glioma progression." (PMID 38886655, 2024). "Simultaneously, we demonstrated that inhibiting p-STAT3 through EZH2 enhances NLRP3 inflammasome activity, promoting glioma pyroptosis and the expression of inflammatory factors IL-1β and IL-18." (PMID 39069522, 2024). "Compared to the normal glioma cell line HA1800, quantitative PCR (qPCR) analysis revealed EZH2 and STAT3 were higher in U87, H4, and A172 (glioma cell lines)." (PMID 39069522, 2024). "Overexpression of EZH2 can suppress the expression of oncogenes like c-myc and AKT in glioma cells, thereby promoting tumor progression." (PMID 38886655, 2024). "By regulating SLC12A5 expression, EZH2 activates the WNK1-OSR1-NKCC1 pathway, enhancing its interaction with ERM to promote glioma migration." (PMID 38886655, 2024). "Because EZH2 acts as a histone methylase, we assessed the H3K27me3 modification level of the PTEN gene in glioma cells." (PMID 39114365, 2024). "Examining the potential molecular mechanism, we found that CBX2 inhibits PTEN transcription by recruiting EZH2 to regulate the H3K27me3 level of the PTEN promoter and thus activates the AKT/mTOR pathway to accelerate glioma progression and TMZ chemoresistance." (PMID 39114365, 2024). "Following these findings, we conducted rescue experiments to further confirm the impact of EZH2 and KCC2 alterations on glioma migration." (PMID 38886655, 2024). "According to previous research, EZH2 can regulate the phosphorylation level of STAT3 and activate pyroptosis in glioma cells through the inflammasome." (PMID 39069522, 2024). "Through analysis of TCGA, Rembrandt and CGGA databases, we discovered a close and statistically significant relationship between EZH2 and CENPA in glioma of all grades." (PMID 39620895, 2024). "The results revealed that sole overexpression of EZH2 promoted glioma migration, while sole overexpression of KCC2 inhibited glioma migration." (PMID 38886655, 2024). "In primary gliomas, DNA methylation downregulates ATRX, inhibiting DNA damage repair through the ATRX/EZH2 complex-PARP1 axis and increasing sensitivity to TMZ." (PMID 39479502, 2024). "Gliomas also demonstrate sensitivity to EZH2 inhibitors, TMZ, and ganciclovir combination therapy, further emphasizing the importance of EZH2 in gliomas." (PMID 38886655, 2024). "The MELK/FOXM1 axis has received more attention in recent years due to its significance in high-grade gliomas, and newer investigations have uncovered other upstream regulators involved in chromatin remodeling, such as SAT1 in the regulation of MELK and EZH2." (PMID 37821870, 2023).
glioma (continued). "In agreement with EZH2 activation by HCMV, we observed a direct interaction between EZH2 and HCMV lncRNA4.9 transcript, likewise between EZH2 and cellular lncRNA HOTAIR transcript, a poor prognosis oncogenic factor for glioma patients." (PMID 37147437, 2023). "Our findings provide compelling evidence showing that SPRY4‐IT1 upregulated EZH2 to induce VEGFA by sponging miR‐101‐3p, thereby achieving cell proliferation and angiogenesis in glioma." (PMID 36479622, 2023). "On the other hand, GAS5 overexpression was shown to increase the amount of PRC2 in glioma cells, with the direct binding of GAS5 to EZH2 resulting in reduced promoter methylation and the induction of miR-424 expression." (PMID 38139448, 2023). "Further, we confirmed that SPRY4‐IT1 regulated the miR‐101‐3p/EZH2/VEGFA signaling axis to induce tumorigenesis and angiogenesis in glioma." (PMID 36479622, 2023). "The silencing of TUG1 or overexpression of EZH2 enhances CSC-like properties and resistance to temozolomide in A172 glioma cells." (PMID 37958880, 2023). "RNA‐sequencing and western blotting confirmed that SPRY4‐IT1 regulated EZH2 and VEGFA expression in glioma cells." (PMID 36479622, 2023). "Studies on EZH2 and microglia/microphages or GAM axis are needed to evaluate their influence in glioma." (PMID 35419058, 2022). "In summary, propofol can enhance the stem-like properties of gliomas through the interaction of GABAAR, Src ZDHCH5, and EZH2." (PMID 35927718, 2022). "The prognostic value of the combined immunoexpression of EZH2 and IDH1 was further explored in a retrospective analysis involving 56 patients with histologically confirmed gliomas in Universiti Kebangsaan Malaysia Medical Centre from 2010 to 2016." (PMID 36292072, 2022). "The present study characterized the EZH2 expression in human GBM-derived cell lines (U87, U251, and D54) and a set of glioma biopsies data from The Cancer Genome Atlas (TCGA)." (PMID 35197928, 2022). "The dysregulation of three necroptosis-related genes (EZH2, LEF1, and CASP1) was significantly related to the OS of glioma patients, especially those with older age, higher WHO grade, wildtype IDH status, and 1p19q codeletion status." (PMID 36389690, 2022). "Taken together, these results indicate that H3.3K27M plays an important role in promoting glioma cell migration and invasion by activating the ꞵ-catenin/USP1/EZH2 signaling pathway." (PMID 36230759, 2022). "We employed IHC to validate the protein expression of EZH2, LEF1, and CASP1 in 43 glioma tissues and matched paracancerous tissues." (PMID 36389690, 2022). "Mechanistically, propofol enhances the stem-like properties of gliomas through GABAAR to increase Src expression, thereby enhancing the palmitoylation of ZDHHC5-mediated EZH2 and Oct4 expression." (PMID 35927718, 2022). "Subsequent multivariate Cox regression analysis indicated that three genes, EZH2, LEF1, and CASP1, exhibited significant prognostic value for glioma." (PMID 36389690, 2022). "Our results verified that high EZH2 immunoexpression was correlated with worse 5-year OS and PFS in gliomas, in line with previously published studies." (PMID 36292072, 2022). "EZH2 was found to be negatively correlated with IDH1 R132H protein expression, in which EZH2 was highly expressed in IDH1 R132H-negative gliomas (p = 0.039)." (PMID 36292072, 2022). "Our study demonstrated that EZH2 was upregulated in human gliomas of WHO grades 1 to 4, with an incidence of EZH2 positivity of 48.2%." (PMID 36292072, 2022). "The EZH2 inhibitor MC4040 reverses the EMT and impairs cell migration and invasion, attenuating the glioma malignant phenotype." (PMID 36230759, 2022). "By inhibiting EZH2, miRNA-101 diminishes promoter occupation of LMO3 by H3K27me3 and prevents its methylation, resulting in glioma suppression." (PMID 35236381, 2022). "Given the complex background of EZH2 in gliomas, we addressed this issue in DMG, using in vivo mouse models, with histone H3 WT (wild type) and Ezh2 manipulation." (PMID 35395831, 2022).
glioma (continued). "Thus, EZH2 could be a diagnosis as wells prognosis biomarker for glioma." (PMID 35419058, 2022). "Enhancer of Zeste-Homolog 2 (EZH2), Enhancer of Zeste-Homolog 3 (EZH3) and H3K27(lysine residue at position 27 of histone 3) KMTs were found at elevated levels in glioma, breast and leukemia CSCs, and are credited with maintaining their quiescent state." (PMID 35563709, 2022). "Thus, high-grade glioma cells may elude the p16 cell cycle checkpoint either via the homozygous deletion of CDKN2A or via the EZH2-mediated transcriptional knockout of p16 protein secretion which means that loss of p16 protein secretion augments proliferative activity." (PMID 34745848, 2021). "In glioma cells, HOXA-AS2 recruits EZH2 to upregulate RND3 and promote the proliferation of glioma cells, thereby accelerating tumor growth." (PMID 33430870, 2021). "The knockdown of AXL imitated the anti-invasive properties of EZH2 silencing, and AXL secretion was detected in human gliomas with elevated EZH2 secretion." (PMID 34745848, 2021). "Phosphorylated EZH2 at Ser21 was reported to activate STAT via its methylation, and to enhance the tumorigenic potential of glioma stem-like cells." (PMID 34725436, 2021). "Both western blotting and RT-PCR results indicated that MAP2K4 and ZDHHC17 were increased in the glioma spheres after 6 Gy radiation or TMZ treatment, similar to EZH2 expression." (PMID 31938047, 2020). "The results of immunohistochemical score displayed that the scores of EZH2 and CD206 were enhanced with the increase of glioma grade in comparison with normal brain tissues (p < 0.05)." (PMID 33363140, 2020). "Protein mass spectrometry was used to identify the tumor suppressor genes up‐regulated by AQB.The effects of HOTAIR ‐ EZH2 inhibitor AQB and CDK4/6 inhibitor Palbociclib on glioma cells lines were examined in vitro and in vivo experiments." (PMID 32508030, 2020). "The results showed that compared with normal brain tissues, the expression of EZH2 and CD206 in glioma clinical samples showed an increasing trend with the elevation of glioma grade." (PMID 33363140, 2020). "The combination of AQB and palbociclib inhibitors has a more pronounced suppression effect on the cell cycle, especially gliomas with high expression of HOTAIR and EZH2 and low expression of CWF19L1." (PMID 32508030, 2020). "Collectively, histone methyltransferase EZH2 inhibited miR-454-3p through methylation modification and promoted m6A modification of PTEN to induce glioma M2 macrophage polarization." (PMID 33363140, 2020). "The results described that EZH2 silencing significantly reduced the secretion of MIP-3α and IL-8 and elevated the secretion of IL-6 in nude mice with glioma." (PMID 33363140, 2020). "In the present study, the in vitro experiments revealed the efficacy and mechanism of action AQB in combination with palbociclib on cell cycle inhibition in glioma cell lines, with a high expression of HOTAIR and EZH2, and a low expression of CWF19L1." (PMID 32508030, 2020). "For instance, BRAF 35, EGFR 36, EZH2 37, MET 38 and mTOR 39 have been reported as potential protein targets for glioma treatment." (PMID 31523189, 2019). "Of note, several drugs directed against epigenetic pathways (e.g., HDACs, mutant IDH1, EZH2, and DNMT) have been clinically tested for different malignancies, including glioma." (PMID 30644073, 2019). "In particular, in glioma, HOXA11-AS functioned as a competing endogenous RNA (ceRNA) for miR-214-3p, which in turn positively regulated the expression of its direct target EZH2." (PMID 31275988, 2019). "In summary, our data provide the first evidence that the EZH2/miR-708/SPHK2/AKT/β-catenin axis controls growth and invasion in glioma cells." (PMID 31171769, 2019).